EPHA4 (EPH receptor A4)
Diseases named in the same sentence as EPHA4 in open-access papers (continued):
Sharing a sentence is not in itself a finding about the gene and the disease.
tumor (60 papers, 2011 to 2025). "In ND2-SmoA1 transgenic mice, loss of ephrin-A5—along with EphA4 and EphA7—significantly reduced tumor size and p-Akt levels." (PMID 41200151, 2025). "EphA2 expression was significantly associated with patient age, while EphA4 and EphA5 with tumor proliferative capacity." (PMID 39839790, 2024). "Some studies have shown that RTKs play an important role in Epstein-Barr virus (EBV)-related tumor formation, because deceased expression of EPHA4 is associated with EBV infection." (PMID 37976136, 2023). "EphA4 was elevated following epithelial to mesenchymal transformation of mammary epithelial cells, which gives tumour cells stem-cell-like traits that are linked to aggressiveness, invasion, and resistance to treatment." (PMID 36830852, 2023). "EPHA4 has been described to promote cell proliferation and migration and was associated with tumour aggressiveness and poor patient survival in human breast and rectal cancer." (PMID 35538064, 2022). "EphB4 cancer cell loss also triggers compensatory upregulation of EphA4 and T regulatory cells (Tregs) influx and their targeting results in reversal of accelerated tumor growth mediated by EphB4 knockdown." (PMID 35725568, 2022). "EPHA4 expression in OC patients correlated with early relapse and showed an adverse clinical association when expressed in both OC tumor cells and tumor-associated macrophages." (PMID 35328669, 2022). "EphA4 is an essential factor for TGFβ-induced migration associated with later tumor stages, worse prognosis, and chemotherapy resistance, and can be regulated by TGFβ." (PMID 34221956, 2021). "EphA5 and A7 expression was significantly positively associated with tumor proliferative capacity (p = 0.006 and p = 0.028, respectively), while EphA4 expression showed a trend of correlation (p = 0.083)." (PMID 24495444, 2014). "EphA4 expression was significantly associated with the presence of inflammation (p = 0.025) and EphA5 expression with tumor proliferative capacity (p = 0.023)." (PMID 24495444, 2014). "However, when EphB4 knock out tumors in mice were treated with EphA4 inhibitor, a significant tumor growth reduction was observed, suggesting that EphA4 plays a compensatory role to enhance tumor growth in vivo following the loss of cancer cell EphB4." (PMID 35725568, 2022). "Furthermore, EphA4 somatic mutations have been identified in a number of tumor types (cbioportal.org)." (PMID 34139238, 2021). "EphA4 and EphA6 are implicated in tumor biology of several cancer types." (PMID 34943502, 2021). "Finally, our data revealed a strong association between high EPHA4 expression and advanced tumor stage, aggressive BLBC molecular subtype and poor prognosis." (PMID 29101386, 2017). "Studies reported that EMT program has positive effect o the expression level of CD90 and EphA4 which are known to participate in interactions among CSCs and tumor-associated monocytes and macrophages (TAMs) and these TAMs create a CSCs niche causing enhanced CSCs activities of carcinoma cells." (PMID 28785557, 2017). "The results we obtained may provide novel information on the mechanisms of host EphA4‐deficiency inhibiting tumor progression mainly via EphA4‐mediated IGF1 production." (PMID 26923183, 2016). "Elevated EphA4 expression was also significantly associated with low stage and presence of inflammation, while enhanced EphA7 expression with older patients’ age, presence of fibrosis and smaller tumor size." (PMID 24495444, 2014). "Consequently, RNF5 silencing or RNF5 loss suppresses PEL-derived xenograft tumor growth, with increased EphA4 levels and decreased oncogenic KSHV viral gene expression and genomic viral DNA loads, providing a novel therapeutic candidate for KSHV lytic infection and KSHV-positive PEL treatment." (PMID 36656913, 2023). "EphA4‐deficient microenvironment could play an important role in impairing the tumor development niche and blocking the vicious cycle to inhibit the tumor progression." (PMID 26923183, 2016).
tumor (continued). "Silencing ephrin-B3 reduces angiogenesis and tumor growth, highlighting the therapeutic potential of disrupting the EphA4/ephrin-B3 axis." (PMID 41200151, 2025). "Here we found that inhibition of EPHA4 phosphorylation induced proliferation of cells cultivated as tumor spheres and would thus be expected to promote tumor growth (Sup." (PMID 37945695, 2023). "The TAMs caused EphA4 activation and stimulated cytokine secretion in the CSC population, resulting in enhanced tumour cell proliferation via Src kinase, phospholipase Cγ1, protein kinase C, nuclear factor kappa B, IL-6, and IL-8 activation." (PMID 36830852, 2023). "In contrast with the oncogenic role of EphA4 that is well-documented on tumor cells, the role of EphA4 on immune cells remains ill-defined." (PMID 37416781, 2023). "In the combination of low EPHA4 expression confirmed via RT-qPCR, the tumor-preventing role and prognostic value of EPHA4 in DLBCL become more convincing." (PMID 37976136, 2023). "Anomalous EphA4 pathway has been linked to neurodegeneration but a correlation has also been established between EphA4 and tumor malignancy through a poorly clarified mechanism." (PMID 36142306, 2022). "To reverse the tumor growth mediated by EphA4, we used a multi-target tyrosine kinase inhibitor, Dasatinib, in the EphB4 knockout tumor-bearing mice." (PMID 35725568, 2022). "Our study demonstrates how the compensatory mechanisms by upregulated EphA4 come into the concert when the preferred binding partner of ephrinB2, EphB4, is lost and by inhibiting EphA4 signaling, tumor growth inhibition can be effectively restored in HNSCC." (PMID 35725568, 2022). "The discordance between the TCGA data and our in vivo findings can be attributed to the fact that in our study, EphA4 was upregulated only when EphB4 was knocked down on the tumor cells." (PMID 35725568, 2022). "FISH analysis and IHC staining also showed that high expression levels of circulating exosomal miR-106b-5p were accompanied by high expression levels of tumour miR-106b-5p and reduced EphA4 expression." (PMID 33741023, 2021). "This study suggested that EphA2, EphA3, EphA4, and EphA5 can act as tumor-inhibiting factors as well as biomarkers for the prognosis of BC." (PMID 34221956, 2021). "We found that the circulating exosomal miR-106b-5p expression level was positively correlated with tumour miR-106b-5p expression levels but negatively correlated with EphA4 expression." (PMID 33741023, 2021). "Previous studies have suggested that EphA4 activation in different tumor cell types can affect cancer progression." (PMID 34139238, 2021). "EphA4, a member of the Eph receptor tyrosine kinase family, has been shown to play different roles in different human tumours." (PMID 33741023, 2021). "Lastly, we provide evidence that in GBM, Ephrin-B3 favors tumor growth by inhibiting EphA4-induced endothelial cell death and we then propose to use this trait in a therapeutic perspective." (PMID 28423606, 2017). "Co-expression of EPHA4 with the TGFβ receptor type-2 also correlated with increased tumor relapse and drug resistance." (PMID 29101386, 2017). "Here, we report that Ephrin-B3 is highly expressed in human biopsies and that it inhibits EphA4 pro-apoptotic activity in tumor cells." (PMID 28423606, 2017). "In the absence of IGF1 administration, the growth retardation of the primary tumor was observed in EphA4‐KO tumor‐bearing mice compared to that of control ‐WT tumor‐bearing littermate mice." (PMID 26923183, 2016). "The plasma level of IGF1 was significantly lower in Epha4‐KO tumor‐free mice compared with ‐WT tumor‐free mice.Similar results were found in tumor‐bearing mice." (PMID 26923183, 2016). "The EphA4‐deleted microenvironment and delayed tumor development reduced the production of G‐CSF resulting in the decrease of splenomegaly and leukemoid reaction including MDSCs, which in turn inhibit the tumor progression." (PMID 26923183, 2016).
tumor (continued). "As we have already mentioned that host EphA4 regulates tumor progression via multiple signal pathways." (PMID 26923183, 2016). "Compared with either the spleen of tumor‐free mice or the spleen of EphA4‐KO tumor‐bearing mouse without IGF1 treatment, the splenic enlargement was conspicuous in the control EphA4‐WT tumor‐bearing mice." (PMID 26923183, 2016). "In the control EphA4‐WT tumor‐bearing mice, the markedly PBL increase usually started from the fourth week after transplant." (PMID 26923183, 2016). "Our study focused on the tumor growth niche by using a different genetic background of the host such as EphA4‐KO and WT to analyze the regulation mechanism of stem‐like niche." (PMID 26923183, 2016). "The hematoxylin and eosin (HE) stained spleen sections showed the severe EMH of expanded granulocyte‐rich red pulp with reduction in white pulp area (lymphocytes) in the control EphA4‐WT tumor‐bearing mice." (PMID 26923183, 2016). "Western blot analysis of tumor tissue harvested from EphA4−/−EphA7−/−Smo, EphA4+/−EphA7−/−Smo, and EphA4+/+EphA7−/−Smo mice revealed expression of p-Akt and PCNA that correlated with actual tumor size." (PMID 26345456, 2015). "Altered expression patterns of EphA4/ephrins are correlated with tumor behaviors, such as invasiveness, vascularization, and metastatic potential." (PMID 24265799, 2013). "The expression of EphA4 in primary tumours significantly correlated with that in metastatic lymph nodes." (PMID 23738943, 2013). "High expressions of EphA2, EphA4, and ephrinA1 significantly correlated with variables related to tumour progression, including the depth of invasion, metastatic lymph nodes, pathological stage, and distant metastasis or recurrent disease." (PMID 23738943, 2013). "Conversely, TQ treatment resulted in the downregulation of several genes overexpressed in GBM cells, including potential oncogenes like AEBP1, MIAT, GHR, LMO1, ELF3, and genes involved in tumor proliferation and migration such as EPHA4, COL3A1, PCDH10, ROBO1, ADAMTS5, PCDH18, ST8SIA1." (PMID 39874307, 2025). "In summary, most Eph receptors (EphA1, EphA2, EphA3, EphA4, EphA5, and EphA7) function as promoters of GC progression, influencing metastasis, tumor invasion, angiogenesis, and drug resistance, while EphA1 has a more complex role depending on tumor differentiation." (PMID 39839790, 2024). "Of note, some EPHs, such as EPHA4, can exert both tumor-promoting and tumor-suppressive functions." (PMID 38612645, 2024). "Notably, EphA4 is expressed not only on tumor cells but also on immune cells in the TME, including T and B lymphocytes 28-30." (PMID 37416781, 2023). "In particular, EphA2, EphA3, EphA4, and EphB4 are promising therapeutic candidates, based on increased expression in tumours and the TME, and drugs targeting these receptors have shown some promise in tumour models, with mixed success in the limited clinical studies performed to date." (PMID 36830852, 2023). "It would be worthwhile to elucidate whether the binding of RNase1 to EphA4 on CD4+ T cells stimulates their migration to tumor tissue for maintaining immune homeostasis." (PMID 37416781, 2023). "Evidence suggests a role of EPHA4 in tumor development and progression." (PMID 36362284, 2022). "The relatively high concentration of serum/plasma hRNase 1 in the tumor microenvironment may predominantly contribute to EphA4 activation via an autocrine or paracrine pathway under low cell density in early stage of tumorigenesis." (PMID 33986289, 2021). "Consistent with the present profiling analyses, EPHA4 expression is associated with basal-like BrCa and EPHA5 has been reported to act as a tumor suppressor, which may be related to abrrant promoter methylation." (PMID 33977106, 2021). "EphA4, which is a member of the large Eph (erythropoietin-producing hepatocellular carcinoma) family of receptor tyrosine kinases, has been shown to play oncogenic and tumour-suppressive roles in many human tumours." (PMID 33741023, 2021).
tumor (continued). "We confirmed that EphA4 is indeed expressed in tumor blood vessels." (PMID 28423606, 2017). "Thus, a potential role of EphA4 as a tumor suppressor in lymphoid malignancies is currently receiving increasing attention." (PMID 28887496, 2017). "However, there is limited information on the effects of EphA4 on tumor microenvironment, which includes the surrounding support connective tissue, hormones, immunoreaction cells, and other humoral growth factors for tumor progression." (PMID 26923183, 2016). "The results showed that the EphA4‐deleted host could inhibit primary tumor growth and tumor metastasis mainly by decreasing the amount of IGF1 synthesis in the circulation and locally tissues." (PMID 26923183, 2016). "Our findings demonstrated that EphA4‐deleted microenvironment impairs tumor‐supporting conditions." (PMID 26923183, 2016). "Thus, we made the dissection for primary tumors isolation, tumor weight measurement, and counting the metastatic tumor foci between the fifth and seventh week of tumor‐bearing EphA4‐KO and ‐WT paired littermate mice." (PMID 26923183, 2016). "EphA4‐KO mice with IGF1 administration showed significant tumor weight gain to almost the WT level." (PMID 26923183, 2016). "EphA4‐deleted host significantly reduced the splenomegaly resulting in a marked reduction in circulating MDSCs, which may be mainly via reduced tumor growth and decreased G‐CSF releasing." (PMID 26923183, 2016). "The mechanism on how EphA4 affected host environment to regulate tumor growth and progression is still unknown." (PMID 26923183, 2016). "Significant tumor weight gain was identified in the IGF1 injected EphA4‐KO tumor‐bearing mice." (PMID 26923183, 2016). "On the other hand, even tumor-suppressive activation of EphA4 was evident in another study." (PMID 23738943, 2013). "However, only EphA4 showed a significant relation between expression in primary tumours and that in metastatic lymph nodes (p = 0.012)." (PMID 23738943, 2013). "Therefore, the differential binding of KLF14 and EGR2 and expression of downstream EPHA4 impact both tumor growth and drug sensitivity, suggesting that chromatin remodeling in different PDMC may interfere with their ability to predict therapeutic outcomes." (PMID 38380561, 2024). "EphA4 promotes cell motility and invasion, and its inhibition could reduce tumor progression." (PMID 39839790, 2024). "To minimize the issues that might be caused by the compound 1-EphA2 association, hereinafter we focused on RNase1 to further pursue how RNase1 contributes to antitumor immunity and whether EphA4 is involved in RNase1-mediated tumor suppression in the breast TME." (PMID 37416781, 2023). "In addition, data mining from the GOBO and ONCOMINE databases indicated that elevated EPHA4 mRNA expression correlated with stage 3 and 4 tumors, poor tumor differentiation, shortened relapse-free survival, positive LN status, and the highly aggressive basal-like subtype." (PMID 34445116, 2021). "We hypothesized that the EphA4‐deleted host may be able to delay the tumor progression." (PMID 26923183, 2016). "It is unknown whether EphA4‐deleted microenvironment affects tumor progression." (PMID 26923183, 2016). "Breast CSCs expressing EphA4 and the MSC/CSC marker CD90, which binds integrins on surrounding cells, were evident at tumour margins in mice, interacting with invading TAMs." (PMID 36830852, 2023). "Here, we demonstrated that RNF5 inhibition suppresses PEL xenograft tumor growth and oncogenic KSHV lytic replication through increased EphA3 and EphA4 levels and decreased downstream pathways." (PMID 36656913, 2023). "EPHA4 and EPHB2 were significantly enriched in the BTY25 line, suggesting a tumor potentially driven by Ephrin receptors." (PMID 36077757, 2022). "Other genes, such as ETV4, ETV5, CCND1, EPHA2, and EPHA4, also play a role in activating the MAPK pathway, promoting tumor resistance to MEKi." (PMID 36437939, 2022).
tumor (continued). "miR-106b-5p targets the EphA4 to activate the ERK pathway and induces the EMT of melanocytes, established the microenvironment characteristics that facilitate tumor metastasis." (PMID 33741023, 2021). "EphA4 appears to have multiple pathways in regulating tumor development beyond IGF1 synthesis, such as the EphA4–FGFR pathway." (PMID 26923183, 2016). "In the absence of IGF1 administration, spleen enlargement was significantly decreased in EphA4‐KO tumor‐bearing mice, and IGF1 treatment was able to markedly increase splenic enlargement of EphA4‐KO tumor‐bearing mice." (PMID 26923183, 2016). "EPHA4, a member of the EPHA receptors, has been demonstrated to be elevated in various human cancers and involved in the tumor progression." (PMID 24932309, 2014). "In double knockout mice lacking EphA4 and EphA7 (EphA4−/− EphA7−/− Smo), MRI and Western blot analyses showed no consistent changes in tumor size, despite correlations between tumor volume, p-Akt, and PCNA levels." (PMID 41200151, 2025). "Furthermore, EPHA4, a shared downstream target gene of KLF14 and EGR2, altered tumor sensitivity to MEK inhibitor treatment." (PMID 38380561, 2024). "EPHA4, a member of the EPH receptors, is closely related to tumor progression." (PMID 28320388, 2017). "The sections of BM showed cancer‐associated myelopoiesis in both EphA4‐KO tumor‐bearing mice without or with IGF1 treatment and control WT tumor‐bearing mice." (PMID 26923183, 2016). "In the absence of IGF1 administration, EphA4‐KO 4T1 tumor‐bearing mice showed significantly reduced tumor metastatic foci compared with that in control WT littermate mice." (PMID 26923183, 2016). "IGF1 treatment showed slightly increased IGF1 level in EphA4‐KO tumor‐bearing mice but the increase was not statistically significant." (PMID 26923183, 2016). "The number of PBL significantly reduced in EphA4‐KO tumor‐bearing mice without IGF1 administration, but EphA4‐KO mice with IGF1 treatment showed an enhanced PBL number almost to the level of WT mice." (PMID 26923183, 2016). "EphA4‐KO tumor‐bearing mice without IGF1 administration showed a significant reduction in G‐CSF circulation level, which was enhanced by IGF1 treatment up to a level similar to that observed in WT tumor‐bearing mice." (PMID 26923183, 2016). "Myeloid cell precursors of EMH were very rare or markedly reduced in the liver of EphA4‐KO tumor‐bearing mice without IGF1 treatment, but markedly increased with IGF1 administration (F‐1, F‐2)." (PMID 26923183, 2016). "Unlike the ephrin-A5 mice, data for the EphA4/EphA7 Smo mice did not yield any consistent patterns of variability in tumor size." (PMID 26345456, 2015). "Efnb3 was detected in the plasma membrane of mouse cells at the AOI but not in the unaffected cortex or the tumor core, while human EPHA4 expression was found in the plasma membrane of the IGCs." (PMID 25365423, 2014). "The results of the study suggest that EPHA4 may promote the motility and invasion of PC cells by up-regulating MMP-2 and Snail, as well as down-regulating E-cadherin, and may become a useful target for the treatment of this tumor." (PMID 39839790, 2024). "Thus, ephrin-A5 could have been investigated as a potential tumor-suppressing ligand through the interaction with its tumor promoting receptors such as EPHA2, EPHA3, EPHA4, EPHA5, EPHA7, EPHA8, and EPHB2 in sarcomas." (PMID 35563562, 2022). "We showed here that, in addition, EphA4 cannot be considered as a classical oncogenic growth factors receptor since it may be able to act as a conditional tumor suppressor in absence of Ephrin-B3." (PMID 28423606, 2017). "The reason behind why IGF1‐stimulated tumor growth could not produce sufficient G‐CSF for splenic EMH to reach WT level is due to EphA4‐FGFR signaling, which regulates the MDSC proliferation." (PMID 26923183, 2016). "However, IGF1 administration did not significantly further increase the tumor weight of the control EphA4‐WT mice." (PMID 26923183, 2016).